EFCAB14 (EF-hand calcium binding domain 14)
Synonyms: KIAA0494
Tractability: PROTAC: its protein half-life has been measured.
Gene: Protein-coding gene on chromosome 1 (46,674,659 to 46,719,146, reverse strand). Ensembl gene ENSG00000159658.
Subcellular location (Human Protein Atlas): Cytosol; Golgi apparatus; Nucleoli
Gene Ontology:
Molecular function: calcium ion binding
Genetic constraint (gnomAD): Loss-of-function variants: 41 observed, 55.31 expected, observed/expected ratio (o/e) 0.74, 90% interval 0.58 to 0.96. The upper end of that interval is the gene's LOEUF score, 0.96, which puts it in group 4 of 6, group 1 being the genes least tolerant of losing a copy. Missense variants: 528 observed, 602.32 expected, observed/expected ratio (o/e) 0.88, 90% interval 0.81 to 0.94. Synonymous variants: 234 observed, 222.11 expected, observed/expected ratio (o/e) 1.05, 90% interval 0.95 to 1.17.
Homologues: Orthologues: chimpanzee EFCAB14 (99% identical), rabbit EFCAB14 (88% identical), dog EFCAB14 (87% identical), pig EFCAB14 (85% identical), macaque EFCAB14 (85% identical), rat Efcab14 (82% identical), mouse Efcab14 (79% identical), guinea pig EFCAB14 (76% identical), tropical clawed frog efcab14 (49% identical).
Diseases named in the same sentence as EFCAB14 in open-access papers:
EFCAB14 is named in the same sentence as 4 diseases in open-access papers, as found by Europe PMC text mining. Sharing a sentence is not in itself a finding about the gene and the disease.
EFCAB14 shares sentences with these, for which no sentence is quoted: osteoarthritis (2 papers); anemia (1); asthma (1); malnutrition (1).